SLC47A1 (solute carrier family 47 member 1)
Description:
Multidrug efflux pump that functions as a H(+)/organic cation antiporter. Plays a physiological role in the excretion of cationic compounds including endogenous metabolites, drugs, toxins through the kidney and liver, into urine and bile respectively. Mediates the efflux of endogenous compounds such as creatinine, vitamin B1/thiamine, agmatine and estrone-3-sulfate. May also contribute to regulate the transport of cationic compounds in testis across the blood-testis-barrier (Probable).
Synonyms: MATE1; FLJ10847
Tractability: Small molecule: a high-quality ligand is known; it belongs to a druggable protein family. Antibody: UniProt places it where antibodies can reach, with high confidence; its Gene Ontology location is reachable by antibodies, with high confidence; UniProt predicts a signal peptide or a membrane-spanning region. PROTAC: ubiquitination databases record sites on it; its protein half-life has been measured; a small molecule that binds it is known.
Target class: Transporter; Electrochemical transporter; SLC47 family of multidrug and toxin extrusion transporters; SLC superfamily of solute carriers
Gene: Protein-coding gene on chromosome 17 (19,495,385 to 19,579,034, forward strand). Ensembl gene ENSG00000142494.
Subcellular location: Cell membrane; Apical cell membrane
Pathways (Reactome):
Transport of small molecules: SLC-mediated transport of organic cations
Gene Ontology:
Molecular function: antiporter activity; L-amino acid transmembrane transporter activity; L-arginine transmembrane transporter activity; polyspecific organic cation:proton antiporter activity; protein binding; putrescine transmembrane transporter activity; thiamine transmembrane transporter activity; transmembrane transporter activity; xenobiotic transmembrane transporter activity
Biological process: amino acid import across plasma membrane; L-alpha-amino acid transmembrane transport; L-arginine import across plasma membrane; putrescine transport; transmembrane transport; xenobiotic detoxification by transmembrane export across the plasma membrane; xenobiotic transport; amine transport; monoatomic cation transmembrane transport; proton transmembrane transport; thiamine transmembrane transport; xenobiotic transmembrane transport
Cellular component: apical plasma membrane; basolateral plasma membrane; plasma membrane; membrane
Genetic constraint (gnomAD): Loss-of-function variants: 55 observed, 62.32 expected, observed/expected ratio (o/e) 0.88, 90% interval 0.71 to 1.11. The upper end of that interval is the gene's LOEUF score, 1.11, which puts it in group 4 of 6, group 1 being the genes least tolerant of losing a copy. Missense variants: 700 observed, 720.32 expected, observed/expected ratio (o/e) 0.97, 90% interval 0.91 to 1.03. Synonymous variants: 284 observed, 297.07 expected, observed/expected ratio (o/e) 0.96, 90% interval 0.87 to 1.05.
Homologues: Orthologues: chimpanzee SLC47A1 (98% identical), macaque SLC47A1 (95% identical), mouse Slc47a1 (78% identical), pig SLC47A1 (78% identical), rabbit SLC47A1 (77% identical), rat Slc47a1 (76% identical), guinea pig SLC47A1 (75% identical), dog SLC47A1 (69% identical), zebrafish slc47a1 (45% identical), zebrafish slc47a4 (41% identical). Paralogues in human: SLC47A2 (49% identical).
Diseases named in the same sentence as SLC47A1 in open-access papers:
SLC47A1 is named in the same sentence as 59 diseases in open-access papers, as found by Europe PMC text mining. Sharing a sentence is not in itself a finding about the gene and the disease. The quoted sentences say what the papers report.
diabetes (11 papers, 2012 to 2023). "For instance, the protective effect of metformin in reducing incidence of diabetes was associated with variation in the SLC47A1 gene in the Diabetes Prevention Program." (PMID 38550950, 2023). "Therefore, our aim was to investigate whether DNA methylation and gene expression of SLC22A1, SLC22A3, and SLC47A1 are associated with diabetes medication in the human liver." (PMID 28947922, 2017). "We next examined if DNA methylation in the SLC22A1, SLC22A3, and SLC47A1 genes was different in the human liver according to diabetes medication." (PMID 28947922, 2017). "Furthermore, DNA methylation in six CpG sites annotated to SLC22A1, one CpG site annotated to SLC22A3 and six CpG sites annotated to SLC47A1 were significantly different with false discovery rate (FDR) less than 5% according to diabetes medication." (PMID 28947922, 2017). "Lower average and promoter DNA methylation of SLC22A1, SLC22A3, and SLC47A1 was found in diabetic subjects receiving just metformin, compared to those who took insulin plus metformin or no diabetes medication." (PMID 28947922, 2017). "However, while SLC22A1 and SLC47A1 had higher expression than SLC22A3, no expression differences were observed for any of the three metformin transporters according to diabetes medication." (PMID 28947922, 2017).
type 2 diabetes (9 papers, 2016 to 2026). "Polymorphisms in SLC47A1 are associated with type 2 diabetes." (PMID 37547318, 2023). "Our simulations suggest that with a total of 2,155 participants randomized to the metformin and placebo control interventions, the DPP was likely underpowered (61%) to observe the interaction between the rs8065082 SLC47A1 variant and metformin in type 2 diabetes incidence." (PMID 27886175, 2016). "The aim of this study was to evaluate pharmacogenetic variation in SLC47A1 (rs2289669) and metformin response in type 2 diabetes patients." (PMID 28775995, 2017). "Our data indicated that the AA or GG genotype of SLC47A1 rs2289669 and the AG genotype of SLC47A2 rs12943590 might affect HOMA-IR in patients with type 2 diabetes." (PMID 36289808, 2022).
Insulin resistance (4 papers, 2016 to 2025). Increased resistance towards insulin, that is, diminished effectiveness of insulin in reducing blood glucose levels. "The variants of SLC47A1 rs2289669 and SLC47A2 rs12943590 could be predictors of insulin resistance in type 2 diabetic patients treated with metformin." (PMID 36289808, 2022). "Xiao and colleagues demonstrated an interaction between SLC47A1 rs2289669 and SLC22A1 rs594709, which affects the blood glucose, insulin level, insulin resistance and blood lipid improvement after metformin treatment in Chinese patients." (PMID 32961860, 2020). "Furthermore, we found that there was an interaction between SLC47A1 rs2289669 and SLC22A1 rs594709, which affected the blood glucose, insulin level, insulin resistance improvement, and blood lipid after metformin treatment." (PMID 26977146, 2016). "Additionally, we found a significant SNP-SNP interaction between SLC47A1 rs2289669 and SLC22A1 rs594709, which affected the improvement of insulin resistance and blood lipid induced by metformin therapy." (PMID 26977146, 2016).
Hypertension (3 papers, 2012 to 2023). The presence of chronic increased pressure in the systemic arterial system. "However, the mechanism of other genes, such as TXNL1P1, PIP5K1C, MIR3147, and SLC47A1, underlining hypertension requires further investigation." (PMID 36869404, 2023).
leukemia (3 papers, 2024 to 2025). A malignant (clonal) hematologic disorder, involving hematopoietic stem cells and characterized by the presence of primitive or atypical myeloid or lymphoid cells in the bone marrow and the blood. "The other pathway involves sterol o-acyltransferase 1(SOAT1) in human pancreatic ductal adenocarcinoma (PDAC) cells and NM-6 leukemia cells deficient in solute carrier family 47 member 1 (SLC47A1) to produce fatty acid cholesteryl esters and enhance iron apoptosis sensitivity." (PMID 40855044, 2025).
pancreatic cancer (3 papers, 2022 to 2024). "Importantly, SLC47A1 constitutes an actionable target for sensitizing pancreatic cancer cells to the pharmacological induction of ferroptosis." (PMID 36575162, 2022). "In human pancreatic cancer cells lacking the lipid flippase solute carrier family 47 member 1 (SLC47A1), ACSL4-driven PUFA-CE production is particularly significant in promoting ferroptosis." (PMID 39534872, 2024). "Alternatively, the suppression of the lipid flippase solute carrier family 47 member 1 (SLC47A1) enhances ferroptosis by favoring the ACSL4–sterol O-acyltransferase 1 (SOAT1) pathway over the ACSL4–LPCAT3 pathway, leading to the production of PUFA cholesterol esters in pancreatic cancer cells." (PMID 39090114, 2024).
chronic myeloid leukemia (2 papers, 2020 to 2025). "For instance, high expression of SLC47A1 has been linked to reduced effectiveness of metformin in metastatic colorectal cancer and limited imatinib uptake in non-responding chronic myeloid leukemia patients." (PMID 39857775, 2025).
diabetes nephropathy (2 papers, 2016 to 2025). "In recent years, researchers have conducted more and more large‐scale GWAS and Mendelian randomization analysis to explore the genetic variation related to diabetes nephropathy, including UMOD, COL4A3, COL20A1, TENM2, SLC47A1, and so forth." (PMID 40931579, 2025).
Alzheimer disease (1 paper, 2023). A progressive, neurodegenerative disease characterized by loss of function and death of nerve cells in several areas of the brain leading to loss of cognitive function such as memory and language. "Thus, in the analysis of the Mayo RNA-Seq dataset for Alzheimer’s disease, four of the DV genes detected in the control vs. AD comparison that have the largest estimated SD ratio above 1 are LTBP2, SLPI, C2orf40, and SLC47A1." (PMID 37790621, 2023).
breast tumor (1 paper, 2022). "Consistent with the siRNA screen, the knockdown of SLC47A1 using small hairpin RNA (shRNA) also sensitized RSL3 and/or erastin to growth inhibition in PDAC, lung tumor cells (A549), breast tumor cells (MCF-7) and ovarian tumor cells (SKOV-3)." (PMID 36575162, 2022).
clear cell renal cell carcinoma (1 paper, 2019). "Survival analysis of the cancer genome atlas (TCGA) dataset showed for the first time that low gene expression of MARC2, cubilin, and SLC47A1 and high gene expression of KRT17 are associated with poor overall survival in clear cell renal cell carcinoma patients." (PMID 31878355, 2019). "In addition, we showed that the low expression of SLC47A1 leads to poor survival of clear cell renal cell carcinoma patients, suggesting it as a prognostic marker for CDC." (PMID 31878355, 2019).
dyspepsia (1 paper, 2025). An uncomfortable, often painful feeling in the stomach, resulting from impaired digestion. "The SNPs rs2289669 (SLC47A1) and rs3792269 (CAPN10) were significantly associated with greater HbA1c reduction, glycemic goal achievement, and risk of dyspepsia." (PMID 41050568, 2025).
glioblastoma (1 paper, 2024). The most malignant astrocytic tumor (WHO grade IV). "Among these SLCs, SLC2A10 has been reported to be associated with ferroptosis in glioblastoma, SLC47A1 has been demonstrated to mediate temozolomide resistance in glioblastoma, while the functions of the other SLCs in glioblastoma remain unclear." (PMID 38687049, 2024).
glioma (1 paper, 2025). A benign or malignant brain and spinal cord tumor that arises from glial cells (astrocytes, oligodendrocytes, ependymal cells). "SLC47A1, GPC1, CAV1, and SLC18B1 are involved in polyamine transport; however, only CAV1 has been extensively studied in gliomas and is involved in stemness and temozolomide resistance." (PMID 40761256, 2025).
head and neck squamous cell carcinoma (1 paper, 2025). A squamous cell carcinoma that arises from any of the following anatomic sites: lip and oral cavity, nasal cavity, paranasal sinuses, pharynx, larynx, and salivary glands. "This analysis demonstrated that SLC47A1 was the only common gene interacting with ALDH3A2 in head and neck squamous cell carcinoma (HNSC), kidney renal clear cell carcinoma (KIRC), lung squamous cell carcinoma (LUSC), and uterine corpus endometrial carcinoma (UCEC)." (PMID 41444219, 2025).
Hypoglycemia (1 paper, 2014). A decreased concentration of glucose in the blood. "SLC22A1 rs628031 polymorphism was marginally associated with risk for hypoglycemia events (P = 0.046; OR = 0.51; 95% CI 0.26–0.99), while SLC47A1 rs2289669 did not influence the risk for hypoglycemia events (P = 0.310)." (PMID 25025077, 2014).
thyroid disorders (1 paper, 2023). "PPI analysis could not link FBXW10 or SLC47A1 genes to a pathway that contributes to thyroid disorders or malignancies." (PMID 37175943, 2023).
cancer (10 papers, 2016 to 2026). A tumor composed of atypical neoplastic, often pleomorphic cells that invade other tissues. "SLC47A1 is also closely associated with the accumulation of anticancer drugs in cancer cells and can influence their efficacy." (PMID 39857775, 2025). "The expression of the multidrug transporter SLC47A1, which is correlated with chemoresistance in cancer cells, is under the control of H3K27me3 modification." (PMID 38539453, 2024). "Furthermore, SLC47A1 is a significant predictor of the chemosensitivity of cancer cells to drugs, such as platinum–acridine compounds." (PMID 39857775, 2025). "A plasma membrane transporter, the solute carrier (SLC) human multidrug and toxin extrusion protein 1 (hMATE1, SLC47A1), emerged as the dominant predictor of cancer cell chemosensitivity to the hybrid agent (Pearson correlation analysis, p < 10–5) across a wide range of tissues of origin." (PMID 32939009, 2020). "Moreover, our observations suggest that the direct inhibition of SLC47A1 (by its knockdown, knockout, or by means of cimetidine) or its indirect inhibition (by the knockdown of PPARA) can sensitize cancer cells to pharmacological ferroptosis induction." (PMID 36575162, 2022).
tumor (6 papers, 2022 to 2025). "The results indicate that SLC43A3, SLC25A43, SLC2A10 and SLC47A1 show sporadic expression in both tumour cells and TAMs." (PMID 38687049, 2024). "In line with our in vitro studies, PPARA-knockdown (PPARAKD) or SLC47A1-knockdown (SLC47A1KD) MIA PaCa2 cells were more sensitive to IKE-induced tumor suppression compared to control groups in vivo." (PMID 36575162, 2022). "It will be interesting to determine the extent that genetic or pharmacological inhibition of PPARA-dependent SLC47A1 expression enhances ferroptosis-mediated tumor suppression in vivo." (PMID 36575162, 2022). "Of note, the presence of drug transporters (e.g., P-glycoprotein (ABCB1), breast cancer resistance protein BCRP (ABCG2), multidrug resistance protein 2 (MRP2) (ABCC2), multidrug and toxin extrusion protein 1 (MATE1) (SLC47A1)) at the BTB also influences the delivery of nanoparticles to the tumor." (PMID 37049234, 2023). "Interestingly, similar to the results obtained from bulk analysis, the single‐cell data showed a higher detection of SLC43A3, SLC2A10, SLC25A43, SLC7A7 and SLC47A1, which are highly expressed in tumour tissues, relative to SLC1A6 and SLC24A4, which are lowly expressed." (PMID 38687049, 2024). "Like the knockdown of PPARA or SLC47A1, hematoxylin and eosin (H&E) staining observed that the combination of IKE and cimetidine resulted in increased necrotic-like changes in tumor tissue compared to the treatment group alone." (PMID 36575162, 2022). "The under-expression of SLC22A1, SLC22A2, SLC47A1, CTR1, and CTR2 leads to reduce uptake of cisplatin whereas the upregulation of ATP7A, ATP7B, MRP1, MRP2, and MRP4 are responsible for increased efflux of cisplatin out of the tumor cell." (PMID 36715825, 2023).
metabolic disease (2 papers, 2019 to 2025). A congenital disorder (due to inherited enzyme abnormality) or acquired (due to failure of a metabolically important organ) disorder resulting from an abnormal metabolic process. "Together, these findings reinforce that both metformin pharmacokinetics (via SLC47A1) and pharmacodynamics (via CAPN10) are subject to genetic regulation, supporting genotype-guided therapy in metabolic disease." (PMID 41050568, 2025).
SLC47A1 also shares sentences with these, for which no sentence is quoted: lactic acidosis (4 papers); pancreatic ductal adenocarcinoma (3); renal disease (3); fibrosis (2); lung carcinoma (2); acute kidney injury (1); acute liver failure (1); ataxia telangiectasia (1); cerebral toxoplasmosis (1); cholestasis (1); collecting duct carcinoma (1); colon cancer (1); E. coli infection (1); fibrosarcoma (1); hepatoma (1); Hyperglycemia (1); hyperuricemia (1); infection (1); kidney cancer (1); kidney failure (1); liver diseases (1); liver failure (1); lung adenocarcinoma (1); lung squamous cell carcinoma (1); metastatic colorectal cancer (1); neurodegenerative disease (1); neuropathy (1); non-small cell lung carcinoma (1); Obesity (1); ovarian tumor (1).
A further 9 diseases each share a sentence with SLC47A1 in 1 paper.